CCAT2 (colon cancer associated transcript 2)
Diseases named in the same sentence as CCAT2 in open-access papers (continued):
Sharing a sentence is not in itself a finding about the gene and the disease.
breast cancer (continued). "In order to determine the role of CCAT2 in regulating luminal mammary tumor initiation and tumor growth in vivo, the pcDNA3.1-mediated overexpression of CCAT2 in MCF-7 cells was transplanted into the fat pad of immunodeficient female nude mice, followed by tracking of the tumor growth." (PMID 36672487, 2023). "Overall, accumulating evidence suggests that CCAT2 is an oncogene and could serve as a useful biomarker and therapeutic target for breast cancer treatment." (PMID 34527584, 2021). "CCAT2 has been identified to promote proliferation, migration, and invasion in a variety of cancers including colorectal cancer, lung cancer, hepatocellular, and breast cancers, and in particular in TNBC." (PMID 33443534, 2021). "Accordingly, CCAT2 could upregulate the expression of Myc in breast cancer, suggesting that the amplification of CCAT2 and Myc might occur simultaneously." (PMID 34527584, 2021). "CCAT2 promoted growth and metastasis of breast cancer by regulating the TGF-β signaling pathway." (PMID 32517807, 2020). "CCAT2 is also thought to be involved in the development of tamoxifen resistance in breast cancer." (PMID 29299178, 2017). "However, further study is warranted in breast cancer patients to consider CCAT2 as a useful biomarker." (PMID 29299178, 2017). "Taken together, these data suggest a potentially significant role for CCAT2 in a subset of breast cancer patients, which could applied as a potential therapeutic target in these patients." (PMID 28480695, 2017). "Moreover, the relative CCAT2 expression level correlated with the overall survival rate of breast cancer patients." (PMID 27608009, 2016). "A knockdown of CCAT2 affects the Wnt/β-catenin signaling pathway, by suppressing β-catenin activity, whose activation leads to the development of human cancers, including breast cancer." (PMID 27608009, 2016). "Similarly, its expression was identified to be up-regulated (∼6.5-fold) in tamoxifen-resistant versus tamoxifen-sensitive MCF-7 and T47D breast cancer cell lines; and as expected, knockdown of CCAT2 facilitated apoptosis and necrosis in tamoxifen-resistant cells." (PMID 29299178, 2017). "Although a previous report has evaluated the associations between 8q24 region amplification and CCAT2 expression in breast cancer patients, to our knowledge, there is no data regarding the association between CCAT2 expression and precise MYC copy number, which should be evaluated in future studies." (PMID 28480695, 2017). "For example, PCA3 (prostate cancer antigen 3, lncRNA) is considered a biomarker in prostate cancer, and the high expression of lncRNAs CCAT2, MALAT1, and NEAT1 is related to worse OS in breast cancer." (PMID 36924407, 2023). "In contrast, other circulating lncRNAs (H19, SPRY4‐IT1, XIST, UCA1, AC026904.1, CCAT1, CCAT2, ITGB2‐AS, and AK058003) were significantly up‐regulated in breast cancer patients compared to controls." (PMID 36274054, 2023). "The subsequent studies have reported that CCAT2 is positively associated with distant metastasis of non-small cell lung cancer, breast cancer, ovarian cancer, cervical cancer and gastric cancer, which suggests that CCAT2 could be a prognostic biomarker for tumor metastasis." (PMID 32230936, 2020). "Knockdown of CCAT2 inhibited MCF-7 and MDA-MB-231 breast cancer cell proliferation and invasion in transwell migration assays by inhibiting WNT/β-catenin signaling." (PMID 30545127, 2018). "CCAT2 expression was higher in MDA-MB-231 and LCC9 TAM-resistant breast cancer cells derived from MCF-7 cells than in parental MCF-7 cells, and knockdown of CCAT2 inhibited the activation of TGFβ signaling in LCC9 and MCF-7 cells." (PMID 30545127, 2018). "It should be also noted that our ERα-dependent lncRNA set does not contain most of the lncRNAs that were previously studied in breast cancer, such as HOTAIR, CCAT2, UCA1, MALAT1, BCAR4, EGOT, SPRY4-IT1 and others." (PMID 26621851, 2016).
breast cancer (continued). "Since the original publication characterizing the CCAT2 transcript in CRC, an additional study examined the prognostic value of CCAT2 in breast cancer." (PMID 25101115, 2014). "Although the role of CCAT2 in up-regulation of MYC expression has been demonstrated in colon cancer in vitro, there is no sufficient data regarding the possible interactions of these two genes in the tumorigenesis process in breast cancer samples." (PMID 28480695, 2017). "In the presence of a specific inhibitor of the ERK/MAPK pathway (U0126), the expression of CCAT2 decreased significantly in the tamoxifen-resistant breast cancer cells compared to normal cells, which suggest that the ERK/MAPK pathway regulates the expression of CCAT2." (PMID 29299178, 2017). "CCAT2 appeared to have higher expression levels in the epithelial component of breast cancer tissues compared with those of non-tumor tissues." (PMID 27608009, 2016). "In vitro studies in breast cancer cell lines confirmed increased migration capability of CCAT2 overexpressing cells independent of genotype." (PMID 25101115, 2014). "For example, Roxana team evaluated the expression of lncRNA CCAT2 by reverse transcription-qPCR and in situ hybridization (ISH) in breast carcinoma tissue and adjacent tissues, which indicated that CCAT2 could be act as a novel biomarker to predict the clinical outcome." (PMID 28938549, 2017). "According to the Pearson correlation analysis, all the circulating levels of lncRNAs in red color were discovered to be positively related to each other in breast cancer patients, except from CCAT1 and CCAT2 that has a negative relation with Z38." (PMID 36274054, 2023). "We further measured the RNA expression levels of CCAT2 by RT-qPCR in a set of 56 unmatched samples (26 non-cancer breast tissues and 30 breast cancer tissues) from OICN and detected significantly increased levels of CCAT2 RNA in tumor samples compared to the non-tumor group (P=0.026)." (PMID 24077681, 2013).
colon cancer (28 papers, 2013 to 2024). "The Colon cancer-associated transcript 2 (CCAT2) gene was first associated with colon cancer; however, it is currently associated with several types of cancer, including prostate cancer." (PMID 35741800, 2022). "Colon cancer-associated transcript 2 (CCAT2), which is located on chromosome 8q24 and expressed in microsatellite -stable colon cancer, was first identified as a single nucleotide polymorphism region." (PMID 35241975, 2022). "LncRNA colon cancer associated transcript 2 (CCAT2) is highly expressed in colon cancer and can promote tumor growth, metastasis and chromosomal instability." (PMID 35115025, 2022). "The CCAT2 lncRNA is encoded by a gene located at human chromosomal region 8q24, which is associated with the occurrence of colon cancer." (PMID 34499007, 2021). "For example, OncolncRNAs CCAT1 and CCAT2 are found greater in all stages of colon cancer and associated with tumor stage, recurrence‐free survival, and overall survival of CRC patients." (PMID 33094859, 2021). "In colon cancer, by interacting with the CFIm complex with allele specific affinities, lncRNA CCAT2 rs6983267 regulates the alternative splicing of glutaminase, resulting in reprogramming of cancer metabolism." (PMID 34336850, 2021). "An intriguing example is rs6983267 SNP (G/T) that resides in the lncRNA locus CCAT2 (Colon Cancer Associated Transcript 2) and is correlated with colon cancer metabolism (enhanced glutaminolysis) and cell proliferation." (PMID 34449663, 2021). "The lncRNA CCAT2 is oncogenic in colon cancer and CCAT2 gene polymorphisms are linked to several types of cancer such as colon, kidney, thyroid, larynx, lung and myeloid cancers in different populations." (PMID 34868956, 2021). "It is worth noting that this genetic variant is also localized inside the CCAT2 lncRNA upregulated in colon cancer and implicated in other human malignancies." (PMID 33551988, 2020). "It has been reported that rs6983267 within CCAT2 altered the expression level of this lncRNA and conferred the risk of colon cancer, implicating rs6983267 as an expression quantitative trait loci (eQTL) in colorectal tissues." (PMID 31398859, 2019). "CCAT2, a novel lncRNA mapping to 8q24, is highly overexpressed in colon cancer and underlies metastatic progression and chromosomal instability in colon cancer." (PMID 28108736, 2017). "For example, colon cancer-associated transcript-2 (Ccat2), a lncRNA mainly located in the nucleus, has been reported to selectively block miR-145 maturation by inhibiting pre-miR-145 export to the cytoplasm in colon cancer cells." (PMID 34035229, 2021). "In the next set of experiments we tested whether the pre-miR-145 level was associated with expression and location of CCAT2 in the modulated colon cancer cells." (PMID 28964256, 2017). "In colon cancer, miR-145 can inhibit the proliferation and differentiation of colon cancer stem cells, but lncRNA CCAT2 can block this effect by preventing the maturation of pre-miR-145 to miR-14521." (PMID 34091587, 2021). "Initial in vitro and in vivo investigations confirmed that overexpressing CCAT2 increased both the proliferation and metastatic potential of colon cancer cells." (PMID 34830370, 2021). "Colon cancer-associated transcripts 1 and 2 (CCAT1 and CCAT2) are two of the more recently identified transcripts with reoccurring implications in different types of cancers." (PMID 34830370, 2021). "CCAT2 expression was reported as being elevated in the plasma of cancer patients with cervical cancer, gastric cancer, colon cancer, lung cancer, and multiple myeloma." (PMID 34830370, 2021). "CCAT2 has been shown to block the maturation of miR-145 by preventing pre-miR-145 export to the cytoplasm from nucleus, controlling colon cancer cell proliferation and differentiation." (PMID 33246471, 2020). "Similar with CCAT2, robust association of CASC8 gene variations was observed with colon cancer and other tumor types." (PMID 31398859, 2019).
colon cancer (continued). "First, the nuclear and cytoplasmic fractions from stable clones of CCAT2 over-expressing colon cancer cells were isolated and the RNA was extracted from these fractions." (PMID 28964256, 2017). "Considering miRNA biogenesis process, we first determined the location of CCAT2 in colon cancer cells." (PMID 28964256, 2017). "We have observed that modulated expression of CCAT2 regulates the expression of miR-145 in colon cancer HCT-116 and HT-29 cells." (PMID 28964256, 2017). "CCAT2 binds to miR-145 and miR-424 in colon cancer and gliomas, respectively." (PMID 34499007, 2021). "For example, lncRNA colon cancer-associated transcript 2 (CCAT2) enhances the activity of Wnt signaling by increasing MYC, miR-17-5p, and miR-20a, ultimately leading to chromosomal instability and metastatic progression in colon cancer." (PMID 33744866, 2021). "CCAT2 partakes in the development of colon cancer by regulating MYC and Wnt." (PMID 34499007, 2021). "Overexpression of CCAT2 increases the levels of multiple molecular markers of CSCs in colon cancer cells, indicating that CCAT2 may be involved in contributing to CSCs development." (PMID 33246471, 2020). "In addition to being oncogenic in colon cancer, upregulation of CCAT2 has been observed in cell lines and clinical specimens of diverse malignancies." (PMID 31398859, 2019). "The opposite results were found in the CCAT2 knockout colon cancer cells." (PMID 28964256, 2017). "Thus, we examined miR-21 and miR-145 levels in CCAT2 overexpressing colon cancer cells as well as in knock down/knockout cells." (PMID 28964256, 2017). "Based on above results, we hypothesized that CCAT2 downregulates miR-145 expression by selectively suppressing its maturation process in colon cancer cells." (PMID 28964256, 2017). "Finally, the dig-labeled pri-miR-145 was mixed with the RNA which was isolated from over-expression or knock out CCAT2 colon cancer CR-HT-29 and HCT-116 cells or corresponding controls, and digested by recombinant human Dicer enzyme." (PMID 28964256, 2017). "Similarly, CCAT2 was first identified in colon cancer during investigations aiming to identify the functional elements associated with the rs6983267 SNP, a locus on the 8q24 “gene desert” often associated with increased predisposition to the development of colon, ovarian, and prostate cancers." (PMID 34830370, 2021). "Colon cancer associated transcript 2 (CCAT2), a newly discovered lncRNA located at a recurrently amplified region (8q24) in cancers, was demonstrated to promote tumor growth, metastasis, and chromosomal instability in colon cancer via upregulation of the proto-oncogene, MYC." (PMID 31398859, 2019). "In contrast, stable up-regulation of CCAT2 decreases mature miR-145 and increases the expression of several CSC markers in colon cancer cells." (PMID 28964256, 2017). "CCAT2 promotes metastasis and chromosomal instability in microsatellite stable (MSS) colon cancer through a mechanism involving transcription factors, oncogenes and microRNAs." (PMID 24077681, 2013). "First described in colon cancer, CCAT1 and CCAT2 both originate from the 8q24.21 chromosomal region, in close proximity with the MYC gene (500 kb and 300 kb upstream, respectively) and encompassing the cancer risk-associated rs6983267 single nucleotide polymorphism (SNP)." (PMID 34830370, 2021). "Our group has recently exposed the reciprocal regulatory mechanism between CCAT2 and the Wnt pathway and furthermore, various studies have shown a positive correlation of TCF4/β-catenin expression with chemoresistance to 5'FU, mostly in colon cancer, but also in BC." (PMID 24077681, 2013).
glioma (27 papers, 2016 to 2025). A benign or malignant brain and spinal cord tumor that arises from glial cells (astrocytes, oligodendrocytes, ependymal cells). "The cancer susceptibility candidate 2 (CCAT2) lncRNA is an oncogenic 1,752 bp lncRNA located on chromosome 8q24.21 that is upregulated in various human cancers, including glioma." (PMID 33980320, 2021). "The expression level of CCAT2 was associated in several cases with chemotherapeutic and radiotherapeutic resistance in gliomas, CRC, thyroid, breast, and esophageal cancers." (PMID 34830370, 2021). "Another lncRNA, cancer-associated transcript 2 (CCAT2), was found to be up-regulated in glioma tissues and positively correlated with tumor stage." (PMID 28187439, 2017). "Studies have shown that some lncRNAs such as HOTAIRM1 and colon cancer-associated transcript 2 (CCAT2), associated with tumorigenesis and cancer development, were upregulated in glioma, while other lncRNAs showing tumor-suppressive functions, such as RP11-838N2.4 and MALAT1, were downregulated." (PMID 34202078, 2021). "In addition, loss of function assay revealed that knockdown of CCAT2 significantly inhibited glioma cell proliferation and tumorigenesis." (PMID 27833083, 2016). "Other studies have highlighted the crucial roles of lncRNA colon cancer-associated transcript 2 (lncRNA-CCAT2) and lncRNA POU Class 3 Homeobox 3 (lncRNA-POU3F3) in glioma-associated angiogenesis." (PMID 40764607, 2025). "For instance, a study has suggested that glioma cells can induce angiogenesis by transferring Linc-CCAT2 to endothelial cells through exosomal transport." (PMID 37727789, 2023). "LncRNA CCAT2 has been shown to activate the Wnt/β-catenin pathway in pediatric gliomas, promoting tumor growth." (PMID 37444408, 2023). "LncRNA CCAT2 has been found to activate the Wnt/β-catenin pathway in glioma cells, contributing to tumor growth." (PMID 37444408, 2023). "Exosomes from the glioma cell line, U87, have higher expression of linc-CCAT2, can deliver linc-CCAT2 to endothelial cells, induce an angiogenic phenotype in vitro and in vivo, and exert anti-apoptotic effects through hypoxia." (PMID 35577352, 2022). "Linc-CCAT2 is overexpressed in glioma tissues and significantly leads to the malignant progression of gliomas." (PMID 35999601, 2022). "CCAT2 also acts as a molecular sponge to downregulate miR-424 and upregulates Chk1, thereby enhancing chemotolerance in glioma cells." (PMID 33980320, 2021). "While lncRNA CCAT2 was overexpressed in glioma cells, together with VEGF-A, expression of miR-424 was observed at low levels." (PMID 34200145, 2021). "CCAT2 enhances cell proliferation and endothelial angiogenesis in glioma by increasing vascular endothelial growth factor A (VEGFA) through miR-424 and activating the PI3K/Akt signaling pathway." (PMID 33980320, 2021). "In glial tumor cells, CCAT2’s role in angiogenesis and apoptosis was investigated through mechanistic studies that revealed that CCAT2 is encapsulated by tumor cells in exosomes, which are subsequently internalized by endothelial cells." (PMID 34830370, 2021). "It has also been shown that lncRNA CCAT2 is overexpressed in glioma tissues and ncU87 cell-released exosomes." (PMID 33912560, 2021). "The regulatory axis between CCAT2/miR-424/CHK1 was proven in gliomas, showing a direct correlation between CCAT2 expression direct inhibition of miR-424 and upregulation of CHK1." (PMID 34830370, 2021). "In glioma, the transfer of linc-CCAT2 to endothelial cells via glioma-derived exosomes resulted in the promotion of angiogenesis via the upregulation of VEGF, TGFβ, and Bcl-2 as well as a reduction of apoptosis via Bax and caspase-3 in vitro." (PMID 31963599, 2020). "Glioma cells release lncRNA CCAT2‐contained exosomes to facilitate angiogenesis and restrain endothelial cell apoptosis." (PMID 33006432, 2020).